IL6 (interleukin 6)
Diseases named in the same sentence as IL6 in open-access papers (continued):
Sharing a sentence is not in itself a finding about the gene and the disease.
COVID-19 (continued). "An inverse correlation between serum sodium and serum interleukin 6 (IL-6) levels (with IL-6 being a crucial cytokine involved in the fatal outcomes of COVID-19 due to a cytokine storm) provides a possible pathogenic link." (PMID 37623461, 2023). "The current study explored IL-6 as a disease progression marker owing to its characteristic role in the COVID-19-associated cytokine storm, reflecting its importance as a pharmacological target." (PMID 38155729, 2023). "Serum levels of IL-6, a pro-inflammatory cytokine associated with faster disease progression and risk of complications in COVID-19, were assessed." (PMID 37240393, 2023). "Increased serum levels of IL-6, IL-8, and IP-10 were associated with a high mortality rate in COVID-19 patients." (PMID 37226245, 2023). "COVID-19 causes a storm of inflammatory factors (increased levels of interleukin-1β, IL-2, IL-6, IL-10, TNF, interferon, etc.), promoting the sympathetic-vagus balance disorder." (PMID 37475861, 2023). "IFITM-3 AG + GG, ACE-2 CT + TT variants, and IL-6 were found to be significant predictors for COVID-19 severity (p < 0.001) in a univariate logistic regression analysis." (PMID 38155729, 2023). "For instance, IL-6 and IL-8 have been associated with diagnostic and COVID-19 severity), while the expression of IFNγ was reduced in severely ill patients." (PMID 37569646, 2023). "Multiple studies have shown that elevated levels of IL-6 in COVID-19 patients were associated with disease severity." (PMID 37175768, 2023). "Among others, high serum IL-6 and IL-1RA levels were found as independent risk factors for mortality from COVID-19." (PMID 36674654, 2023). "Tocilizumab is an IL-6 receptor antagonist, and a plasma level of IL-6 >30 pg/mL has also been associated with both severe COVID-19 and response to treatment." (PMID 36851508, 2023). "IL-1, another key proinflammatory cytokine, had the best correlation with COVID-19-associated thrombotic events compared to IL-6 and TNF-α in one study." (PMID 36979908, 2023). "Critical and fatal COVID-19 outcomes in adults have been associated with elevated levels of mostly IL-6, IL-1β, and TNF-α, along with a reduced and delayed production of type I IFNs." (PMID 37047752, 2023). "Genetic variants in IL6R known to down-regulate IL-6 signalling are associated with improved Coronavirus Disease 2019 (COVID-19) outcomes, a finding later confirmed in randomised trials of IL-6 receptor antagonists (IL6RAs)." (PMID 36716318, 2023). "In patients with venous thromboembolism in association with COVID-19, laboratory tests indicate high levels of prothrombotic markers (fibrinogen and D-Dimer), and inflammatory markers (C reactive protein, IL-6), which are related to hypercoagulable state." (PMID 36851619, 2023). "Of note, pathogenic GM-CSF-secreting T cells were linked to the recruitment of pro-inflammatory IL-6-secreting monocytes and severe lung pathology in COVID-19-infected subjects." (PMID 37324739, 2023). "COVID-19 patients are more susceptible to inflammatory responses as they secrete excessive IL-6 cytokines and have a high chance of developing post-hepatectomy liver failure (PHLF) following hepatectomy." (PMID 36671484, 2023). "A growing body of evidence suggests that plasma IL-6 levels are associated with disease severity in COVID-19." (PMID 37650680, 2023). "Interleukin-6 (IL-6), inflammatory cytokine released by macrophages increase in patients with severe COVID-19 disease and is associated with complications in COVID-19 patients with the development of cytokine storm, leading to damaged lungs and other organs." (PMID 37790205, 2023). "Some studies demonstrated that the use of IL-6 blocking agents reduced the risk of poor outcomes and secondary infection in hospitalized COVID-19 patients and was linked to decreased 28-day all-cause mortality and a shorter hospital stay." (PMID 37143167, 2023).
COVID-19 (continued). "SARS-CoV-2 promoted secretion of numerous cytokines, with rapid upregulation of IL-6 (23 fold), a key cytokine implicated in COVID-19 severity, while the anti-inflammatory cytokine IL-1049,50 decreased over time." (PMID 37205380, 2023). "It has been suggested that low lymphocyte count (LC) as well as high serum IL-6 level is associated with a worse outcome in COVID-19, even though these biomarkers are poorly specific and have limited prognostic power." (PMID 37097384, 2023). "IL-6 has been reported to be the leading cause of inflammatory response in severe COVID-19 and emerged as an important regulator of Th1/Th2 differentiation, promoting the IL-4-dependent induction of Th2 differentiation and inhibiting Th1 differentiation." (PMID 37685858, 2023). "More specifically, IL-6 levels are significantly elevated and associated with adverse clinical outcomes in patients with COVID-19, playing a significant role in the phase of hyperinflammatory response." (PMID 37637614, 2023). "The high levels of IL-6, being associated with severe COVID-19, have been shown to reduce the expression of perforin and granzyme B in NK cells, subsequently reducing their cytolytic activity." (PMID 37065291, 2023). "Increased levels of IL-6 were found to be significantly associated with adverse clinical COVID-19 outcomes such as ICU admission, acute respiratory distress syndrome (ARDS), and death." (PMID 37095536, 2023). "It has been suggested that IL-6 polymorphisms should be considered as a critical factor in the development of targeted therapies against COVID-19." (PMID 38138102, 2023). "Neutrophilia has been identified as a predictor of poor outcomes in COVID-19 because severe disease is linked to an increased neutrophil-to-lymphocyte ratio and elevated expression of the neutrophil-related cytokines IL-8 and IL-6 in the serum." (PMID 37834246, 2023). "Severe COVID-19 and mortality have been linked to platelet degranulation, low platelet count, and increased levels of IL-6." (PMID 36983995, 2023). "A high concentration of the acute phase response stimulating cytokine IL-6 is related to an increased risk for severe COVID-19." (PMID 36793739, 2023). "An observational study revealed that hospitalized patients with COVID-19 who had hyperglycaemia demonstrated elevated levels of IL-6 and D-dimer, two markers associated with inflammation and a procoagulant state." (PMID 37511334, 2023). "Our findings indicate that IL-6, IL-8, and IL-10 serum levels are significantly increased in COVID-19 but are associated with poor predictive ability regarding disease severity and the need for oxygen therapy." (PMID 37969879, 2023). "The role of IL-6 as a driver of the COVID-19 associated cytokine storm led to the use of IL-6 antagonists in COVID-19 treatment." (PMID 37917760, 2023). "Due to the non-involvement of JAK2 in type I or type II interferon-related cell signaling, selective JAK2 inhibitors are the preferred treatment choice for suppressing IL-6-GM-CSF-signaling-in COVID-19-associated cytokine storms." (PMID 37021053, 2023). "Under such conditions, SARS-CoV-2-induced IL-6 release increases uncontrollably, thus contributing to the development of the cytokine storm associated with severe cases of COVID-19." (PMID 37759738, 2023). "In path c, SB203580 can affect p38, while abnormalities in p38, IL-6, and tumor necrosis factor-α (TNFα) have all been shown to be associated with COVID-19." (PMID 37632414, 2023). "Numerous markers of inflammation have been associated with the clinical severity of COVID-19; higher values of IL-6, CRP, and D-dimer have been found in severe and critical forms of COVID-19." (PMID 37631910, 2023). "If an IL-6 level is more than 6.99 pg/mL, then the patient has a 29 times risk of suffering from COVID-19 and if the NLR level is more than 4.18 pg/mL, then the patient has a 26 times risk." (PMID 38099004, 2023).
COVID-19 (continued). "Sarilumab, Tocilizumab, and siltuximab are existing FDA-approved IL-6 inhibitors for rheumatoid arthritis and COVID-19 to reduce damages caused by IL-6-induced inflammation." (PMID 36986550, 2023). "Consistent with prior reports, IL-6, well-known to associate with poor survival during COVID-19, IL-27, and IL-15 were also observed to stratify survival, but IL-6 displayed a lower hazard ratio than IL-18." (PMID 36894537, 2023). "Many host biomarkers have been associated with COVID-19 disease severity including soluble triggering receptor expressed on myeloid cells 1 (sTREM-1) and interleukin-6 (IL-6)." (PMID 37752433, 2023). "In COVID-19, IL-6 is the most prominently elevated cytokine and elevated IL-6 levels are strongly associated with poorer outcomes." (PMID 37119516, 2023). "Similar to MK, low vitamin D levels are associated with increased inflammatory markers, such as IL-6, in COVID-19 patients at risk of developing severe inflammatory conditions and higher mortality rates." (PMID 36831641, 2023). "In COVID-19 cases, several cytokines are associated with rapid disease progression and a higher complication rate, and interleukin-6 (IL-6) is the most notable cytokine among them." (PMID 37896795, 2023). "On the other hand, the single models revealed that salivary and serum IL-6 levels had a significant association with COVID-19 (P values: < 0.001 and < 0.001, respectively) and periodontitis severity (P values: 0.002 and 0.006, respectively)." (PMID 37568161, 2023). "It is interesting to note that in COVID-19 cases, higher IL-6 levels have been linked to higher mortality." (PMID 38131979, 2023). "Immune deregulation associated with COVID-19 along with treatment with anti-interleukin-6 (anti-IL-6) agents, such as tocilizumab and corticosteroids, make these patients susceptible to fungal infections." (PMID 36836357, 2023). "Elevated levels of IL-6, a main pro-inflammatory mediator, have been associated with a poorer prognosis in COVID-19 patients." (PMID 37047702, 2023). "Research about the mechanisms underlying COVID-19 immunopathology early identified IL-6 as a deleterious factor and proposed this cytokine as one of the main therapeutic targets to be blocked to improve patient survival and outcome." (PMID 36817433, 2023). "The combination of cortizole plus anti-IL-6 or anti-IL-1 agents has been proven to be significantly predisposed to blood stream infections (BSI) in COVID-19 patients." (PMID 36830290, 2023). "We also found robust new evidence that higher levels of inflammatory biomarkers (CRP, IL-6) at admission are associated with COVID-19-related death and disease severity." (PMID 37204441, 2023). "IL-6 is also likely to cause cardiomyopathy by promoting myocardial dysfunction, which is often observed in patients with critical forms of COVID-19." (PMID 36675242, 2023). "Viremia seen secondary to COVID-19 causes cytokine storm, where there is an excessive release of pro-inflammatory cytokines such as IL-1, IL-6, and TNF-α." (PMID 37123703, 2023). "IL-6, among cytokines, has been shown to be associated with more severe forms of COVID-19, probably as a result of the induced cytokine storm." (PMID 36986336, 2023). "IL-6, which is primarily linked to macrophages and dendritic cells (DCs), is one of the deleterious cytokines in COVID-19 linked with severe clinical conditions." (PMID 37767093, 2023). "In conclusion, we demonstrated that serum IFN-α levels strongly predict hypoxemic respiratory failure in the early phases of COVID-19 by the Delta and the precedent variants, as do IL-6 levels." (PMID 37731495, 2023). "Upon activation, neutrophils and monocytes copiously release various inflammatory cytokines, including IL-8, TNF-α, and, most notably, IL-6, which has been associated as an indicator of mortality among severe COVID-19 patients." (PMID 36634048, 2023).
COVID-19 (continued). "We recommend a serial examination of IL-6 level at the admission and during hospitalization in COVID-19 children as well as a larger and multicenter study on risk factors for COVID-19 mortality in children." (PMID 37889917, 2023). "IL-6 level was also associated with severity of COVID-19 (per 5 pg/ml increase: SRR 1.13 [95% CI 1.03, 1.25], n=6 studies, moderate certainty of evidence)." (PMID 37204441, 2023). "In the present study, we re-evaluated the correlation between COVID-19 severity and the enhancement of IL-6 production caused by myeloid cells in the presence of the N protein." (PMID 37896795, 2023). "Further PPI network analysis, differential analysis, and molecular docking revealed that the critical component quercetin affects the inflammatory response caused by COVID-19 through the core targets IL-6 and IL-10." (PMID 38050310, 2023). "The increase of pro-inflammatory cytokines, especially IL-6, is a characteristic of moderate to severe COVID-19, which can cause endothelial dysfunction, increase vascular permeability, and aggravate blood–brain barrier (BBB) dysfunction." (PMID 37867774, 2023). "IL-6 is associated with the severity of COVID-19, and anti-IL-6 receptor antibodies, such as tocilizumab and sarilumab, can alleviate the ordinal scale of symptoms." (PMID 37515185, 2023). "Remarkably, significantly elevated IL-6 levels have been reported in COVID-19 patients, which is associated with adverse clinical outcome." (PMID 38116398, 2023). "On the other hand, FFAR2 and FFAR4 have been shown to downregulate Th2 inflammatory pathways implicated in cytokine storm in severe COVID-19 cases, including inflammatory cytokines IL-1β and IL-6." (PMID 37515117, 2023). "A preliminary report suggested that the need for mechanical ventilation is connected to elevated Interleukins 6 (IL-6) levels and that mildly raised IL-6 levels are sufficient to identify COVID-19 individuals at high risk of respiratory failure." (PMID 35662927, 2022). "We hence propose that IL6 upregulation is associated with higher inflammatory status and damage in COVID-19 patients." (PMID 36518355, 2022). "Again, this negative correlation was only observed in the severe group and the result corroborates a previous finding in COVID-19 pregnant women (first trimester) that associated high IL-6 with low levels of serum Zn2+." (PMID 36016660, 2022). "The association between IL-6 in samples from patients and COVID-19 led to an increase in KYNA, KYN, and PA." (PMID 35281455, 2022). "For example, severe COVID-19 was linked to changes in IL-13, IL6 and IL-1B, and multiple chemokines (e.g. CCL20, CCL27, CXCL10)." (PMID 36171541, 2022). "Other studies have similar findings, with elevated IL-6 predicting the risk of arrhythmias in COVID-19 patients." (PMID 36135437, 2022). "Rapidly, activation of the innate immune response and hypercytokinemia occur in COVID-19 patients, activated pathogenic Th1 cells secrete proinflammatory cytokines, such as GM-CSF and IL-6." (PMID 36147356, 2022). "In severe COVID-19, in fact, increased levels of IL-6 have been found to be associated with higher viral load, lymphopenia and neutrophilia, systemic inflammation, hypoxemia, and poor prognosis." (PMID 35340805, 2022). "In individuals with COVID-19, one of the primary inflammatory agents that causes inflammatory storm is IL-6." (PMID 36506506, 2022). "Immune dysregulation, a hallmark of COVID-19 course and severity, is mainly orchestrated by cytokines and chemokines (e.g., IL-6, IL-1β, IL-8, IL-18, TNF-a) that are identified as tumorigenesis drivers." (PMID 36298472, 2022). "Some studies have reported that IL-6 is an independent biomarker associated with outcomes in COVID-19 patients." (PMID 35204430, 2022). "IL-6 has been implicated as one of the chief mediators responsible for acute respiratory distress syndrome (ARDS) in COVID-19." (PMID 35239650, 2022).
COVID-19 (continued). "Serum cytokine levels that are elevated in patients with COVID-19-associated cytokine storm include interleukin-1β, interleukin-6, IP-10, TNF, interferon-γ, macrophage inflammatory protein (MIP) 1α and 1β, and VEGF." (PMID 35353232, 2022). "A proposed pathogenetic mechanism involving the role of interleukin (IL)-10 and IL-6 can be considered when analyzing the association between aspergillosis and COVID-19." (PMID 35050031, 2022). "Previous study has shown that inhibition of IL-6, a signature cytokine of COVID-19, is associated with improved glycocalyx integrity and thus reduced vascular permeability in the setting of cytokine overexpression." (PMID 35215285, 2022). "A recent prospective meta-analysis demonstrated that interleukin-6 antagonists are associated with lower all-cause mortality in hospitalised patients with COVID-19, compared with usual care or placebo." (PMID 35802687, 2022). "A recent study demonstrated that lower expression of IL-6, as a result of genetic variant, showed protective effects against critical conditions in patients with COVID-19." (PMID 36182930, 2022). "Patients developing severe forms of COVID-19 generally show strong systemic inflammation associated with increased cytokine release, as suggested by elevated concentration of interleukin (IL)-6, C-reactive protein (CRP), D-dimer, and ferritin." (PMID 35214651, 2022). "Elevated, or abnormal soluble biomarkers such as IL-6, D-Dimer or fibrinogen indicate an increased risk for thrombosis or a host immune response in COVID-19." (PMID 36131342, 2022). "We found that the frequency of protective allele G in IL-6 rs2069837 was 0.09 in patients with critical COVID-19 and 0.20 in the controls in our cohort." (PMID 35368020, 2022). "Elevated IL-6 levels are associated with poor prognosis in COVID-19, including respiratory failure and death." (PMID 36503381, 2022). "Our findings demonstrated that T cells specific for SARS-CoV-2 are elevated in the blood of those with pulmonary PASC and are associated with increased IL-6, a cytokine strongly associated with COVID-19 severity, and decreased lung function." (PMID 35617421, 2022). "The marked increase in CXCL10 and IL-6 corroborates previous studies describing the immune response in COVID-19 patients associated with disease severity and progression." (PMID 36451835, 2022). "Next, we have evaluated the association between IL-19 and IL-6 levels in saliva of severe COVID-19 cases with the survival outcomes of these patients." (PMID 36163397, 2022). "Since elevated IL-6 levels are associated with COVID-19 severity, blocking IL-6 signaling has been proposed for treating patients with COVID-19." (PMID 36419185, 2022). "Analyses of cytokines have shown that serum levels of IL-1β, IL-6, IL-10, IL-23, IL-33 and Gal-1 are in significant positive association with increased COVID-19 severity." (PMID 35075140, 2022). "APD prolongation observed with IL-6 + AZM + HCQ led to QTc prolongation thereby increasing the arrhythmic risk for COVID-19 patients." (PMID 35058480, 2022). "There was an inverse association between serum IL-6 concentrations and absolute blood count of lymphocytes in COVID-19 patients, a finding consistent with the results of other studies." (PMID 35721343, 2022). "IL-6 is an acute-phase inflammatory mediator that rises within 2 to 3 hours of infection and is associated with a poor prognosis in COVID-19 patients, reflecting the intensity, degree of pulmonary inflammation, and infection." (PMID 36381779, 2022). "A current matter of debate and future investigations is if an IL-6 and IL-1 blockade truly offers advantages over the standard management in COVID-19, particularly if associated with acute cardiac injury." (PMID 35888173, 2022). "Studies from 2020 showed that the IL-6-JAK-STAT3 pathway is strongly associated with the severity of COVID-19 symptoms." (PMID 35562935, 2022).